C5AR1 (complement C5a receptor 1)
Diseases named in the same sentence as C5AR1 in open-access papers (continued):
Sharing a sentence is not in itself a finding about the gene and the disease.
renal disease (6 papers, 2017 to 2025). "In animal models of renal disease, blocking C5aR1 resulted in reduced small vessel inflammation and neutrophils activation in ANCA-associated glomerulonephritis." (PMID 39857400, 2025).
infectious disease (5 papers, 2016 to 2025). A disorder directly resulting from the presence and activity of a microbial, viral, or parasitic agent in humans. "For example, the different role of C5aR1 and C5aR2 inhibition in these diseases is poorly understood, and inhibition of C5 activation for prolonged time periods results in increased susceptibility to infectious diseases and other undesired effects." (PMID 33917266, 2021). "A large body of research has demonstrated that C5a/C5aR1 signaling contributes to the pathogenesis of a wide range of inflammatory and immunological diseases, but its participation in infectious disease is less known." (PMID 29263309, 2017).
colorectal (4 papers, 2019 to 2026). "Taken together, these findings further prove the prominent role of C5aR1 in initiating CRC and suggest that C5aR1 antagonists, such as PMX205, may hold great potential for preventing colorectal tumorigenesis." (PMID 32754267, 2020).
peripheral neuropathy (3 papers, 2021 to 2023). A disorder affecting the peripheral nervous system. "Activation by the interaction of C5a and its receptor, C5aR1, triggers a cascade of events that are involved in the pathophysiology of peripheral neuropathy and painful neuro-inflammatory states." (PMID 36839876, 2023). "C5/C5aR1 axis modulators could represent a new strategy to treat complement-related peripheral neuropathies." (PMID 33917266, 2021). "Recent evidence has underscored the importance of complement component C5a and its receptor C5aR1 in inflammatory and neuropathic pain, indicating that C5a/C5aR1 axis activation triggers a cascade of events involved in pathophysiology of peripheral neuropathy and painful neuro-inflammatory states." (PMID 33917266, 2021).
brain disorder (2 papers, 2019 to 2023). A disease affecting the brain or part of the brain. "Inhibition of C5aR1 also resulted in behavioral abnormalities in both sexes and MRI-detected brain microstructural alterations in adult male, suggesting that C5aR1 played a functional role in neurogenesis in mammals and provided mechanistic insight into complement-related brain disorders." (PMID 31011487, 2019).
metabolic disorders (1 paper, 2025). "The C5a-C5aR1 pathway, a key hub connecting metabolic disorders and inflammatory fibrosis, plays an important role in promoting the development of MAFLD through participating in the pathological processes at various stages through multidimensional regulation." (PMID 41373839, 2025).
neurological diseases (1 paper, 2017). "The in vitro data here thus suggest that the use of a C5aR1 antagonist could be beneficial in neurological diseases in which complement activation generating C5a occurs." (PMID 28078911, 2017).
C5AR1 also shares sentences with these, for which no sentence is quoted: Arthritis (14 papers); cholangiocarcinoma (5); IgA nephropathy (5); lupus nephritis (5); paroxysmal nocturnal hemoglobinuria (5); atypical hemolytic-uremic syndrome (4); cardiovascular diseases (4); Huntington disease (4); inflammatory bowel disease (4); lymph node metastasis (4); nasopharyngeal carcinoma (4); preeclampsia (4); staphylococcus aureus infection (4); age-related macular degeneration (3); chronic GVHD (3); immune diseases (3); kidney cancer (3); neuromyelitis optica (3); renal carcinoma (3); renal failure (3); acute lung injury (2); allergic contact dermatitis (2); autoimmune hemolytic anemia (2); autoimmune uveitis (2); bone fracture (2); chronic kidney disease (2); glaucoma (2); lymphoma (2); microscopic polyangiitis (2); neuroblastoma (2).
A further 100 diseases each share a sentence with C5AR1 in 2 papers or fewer.